CMKLR1 (chemerin chemokine-like receptor 1)
Diseases named in the same sentence as CMKLR1 in open-access papers (continued):
Sharing a sentence is not in itself a finding about the gene and the disease.
colitis (8 papers, 2015 to 2023). Inflammation of the colon. "Clinical and histopathology scoring showed that mice transplanted with Cmklr1–/– cells (t-KO) developed a more severe GI GvHD, associated with colitis, as compared with WT-transplanted (t-WT) mice." (PMID 36883565, 2023). "In order to address the role of CMKLR1 in a more specific mouse model of intestinal inflammation, we evaluated the susceptibility of Cmklr1-KO mice in a model of acute dextran sulfate sodium–induced (DSS-induced) colitis." (PMID 36883565, 2023). "Mice deficient in CMKLR1 developed DSS-induced colitis in a delayed time course, albeit ultimately presenting with a similar disease activity." (PMID 30369924, 2018). "Histological analysis of the mucosa verified more severe microscopic inflammation, epithelial disruption, and loss of crypt architecture in Cmklr1-KO colon tissues versus WT ones, supporting the involvement of CMKLR1-expressing cells in the protection from colitis development." (PMID 36883565, 2023). "With the observation that bioactive chemerin levels increased both locally and systemically following the induction of IBD, and that CMKLR1 was the only signaling chemerin receptor to exhibit parallel changes in expression, we investigated the impact of CMKLR1 loss on colitis." (PMID 26265756, 2015). "At sacrifice, Cmklr1-KO mice showed shorter colon length, an additional parameter for the evaluation of experimental colitis." (PMID 36883565, 2023). "Starting from day +5 after DSS administration, both WT and Cmklr1-KO mice displayed an increase in clinical colitis." (PMID 36883565, 2023). "An exacerbated inflammatory phenotype and an increased intestinal permeability were also observed in Cmklr1-KO mice in the model of DSS-induced colitis." (PMID 36883565, 2023). "One of them showed that deficiency in the receptor for chemerin (chemokine-like receptor 1 (CMKLR1)) can be followed by the development of DSS-induced colitis in a delayed period of time." (PMID 36235636, 2022). "We previously demonstrated that CMKLR1 KO mice develop clinical signs of DSS-induced colitis more slowly than wildtype mice, which supports the latter findings." (PMID 30225164, 2018). "Bioactive chemerin is a potent chemoattractant for cells that express CMKLR1 and the current study demonstrated that the increase in CMKLR1 expression in DSS-induced colitis resulted at least in part from increased cell infiltration into the colon." (PMID 26265756, 2015). "To do this, we performed the DSS-induced colitis model with 6- to 8-week-old CMKLR1 wild-type (WT), heterozygous (HET), or knockout (KO) littermate mice and monitored the development of colitis." (PMID 26265756, 2015). "Similarly, Cmklr1-KO mice used both as transplant recipients of our GvHD model and in a DSS-induced colitis model showed a very severe intestinal pathology, associated with an increased tissue inflammation." (PMID 36883565, 2023). "Similarly, Cmklr1-KO recipient mice showed increased intestinal pathology in both allogeneic transplant and dextran sulfate sodium–induced colitis." (PMID 36883565, 2023). "Additionally, CMKLR1 KO mice develop signs of clinical illness more slowly in an experimentally-induced colitis model." (PMID 30225164, 2018). "Additionally, a high abundance of Prevotella is correlated with the prevalence of UC in humans and increased epithelial inflammation in a colitis mouse model, which is consistent with CMKLR1 KO mice exhibiting slower disease progression." (PMID 30225164, 2018). "Thus, the constitutive loss of CMKLR1 altered some systemic inflammatory parameters both basally and in response to DSS-induced colitis." (PMID 26265756, 2015). "Surprisingly, constitutive loss of CMKLR1 is not sufficient to prevent the induction of colitis although CMKLR1 KO mice develop illness more slowly." (PMID 26265756, 2015).
colitis (continued). "Surprisingly, while loss of CMKLR1 expression delayed the progression of DSS-induced colitis, it did not ultimately confer protection against disease severity." (PMID 26265756, 2015). "The phenotype achieved following DSS-induced colitis in CMKLR1 KO mice was relatively modest and it is important to note that this may be a result of constitutive loss of CMKLR1." (PMID 26265756, 2015). "Chemerin deficient mice and animals with lack of intestinal epithelial cell CMKLR1 were more sensitive to microbiota-driven colon inflammation." (PMID 36438059, 2022). "We show that while a loss of CMKLR1 does not protect against development of DSS-induced colitis, CMKLR1 KO mice have a slower onset of clinical illness and altered systemic inflammatory parameters." (PMID 26265756, 2015). "We hypothesized that mice lacking CMKLR1 would be protected from inflammatory damage and illness associated with DSS-induced colitis." (PMID 26265756, 2015). "CMKLR1 knockout could, however, neither prevent nor improve dextran sulfate sodium (DSS) colitis." (PMID 36438059, 2022).
Glucose intolerance (8 papers, 2014 to 2022). Glucose intolerance (GI) can be defined as dysglycemia that comprises both prediabetes and diabetes. "For example, chemerin KO mice exhibit exacerbated glucose intolerance on an HFD and CMKLR1 KO mice exhibit differences in adiposity and glucose tolerance when fed an HFD compared to a low-fat diet." (PMID 30225164, 2018). "Notably, all of chemerin, CMKLR1 and GPR1 mutant mice display glucose intolerance." (PMID 29848608, 2018). "This is consistent with previous reports showing no or little effect on glucose homeostasis in CMKLR1-knockout mice whereas GPR1-knockout mice on high-fat diet have increased glucose intolerance compared to wild-type mice." (PMID 35711300, 2022).
hepatocellular carcinoma (8 papers, 2016 to 2024). A malignant tumor that arises from hepatocytes. "It was also reported that chemerin suppressed metastasis of hepatocellular carcinoma cells through the CMKLR1-PTEN-AKT axis." (PMID 39104601, 2024). "Recently, CMKLR1 was found to be expressed in a subset of myeloid-derived suppressor cells (MDSCs) in hepatocellular carcinoma." (PMID 29221117, 2017). "Interestingly, chemerin was previously reported to increase PTEN activity in hepatocellular carcinoma cells, by disrupting a direct interaction with CMKLR1 leading to ubiquitination and degradation of the protein." (PMID 34524600, 2022). "Additionally, CMKLR1 is expressed at high levels in monocytic MDSCs in hepatocellular carcinoma." (PMID 29221117, 2017). "While there is evidence that chemerin and CMKLR1 support tumorigenesis in glioblastoma, gastric cancer, squamous esophageal cancer and squamous cell carcinoma of the oral tongue, an anti-tumorigenic effect has been suggested in melanoma, hepatocellular carcinoma and non-small cell lung cancer." (PMID 29221117, 2017).
neuroblastoma (8 papers, 2017 to 2023). Neuroblastoma (NB) is the most common solid, extracranial childhood tumor. "Tumor-associated macrophages (TAMs) have been shown to promote neuroblastoma tumorigenesis, and CMKLR1 expression in macrophages can be stimulated by mammary and lung carcinoma cells." (PMID 29221117, 2017). "Since that previous study, α-NETA has been employed to block the chemerin/CMKLR1 axis in CNS-related diseases, including preeclampsia and neuroblastoma." (PMID 35459783, 2022). "In neuroblastoma, high CMKLR1 expression correlates with decreased survival and blocking CMKLR1 reduced cell viability of neuroblastoma cells in vitro and tumor progression in vivo." (PMID 34359687, 2021). "Previously, primary esophageal squamous cancers were shown to express CMKLR1; neuroblastoma cells also express both receptors and there is evidence that chemerin acts via CMKLR1 in an α-NETA sensitive mechanism to increase MMP-2 to promote tumor growth." (PMID 30719206, 2019). "α-NETA reduced the clonogenicity and viability of CMKLR1+ neuroblastoma cell lines in vitro, and reduced tumor growth in vivo in a preclinical neuroblastoma model." (PMID 31073181, 2019). "Significantly, inhibition of CMKLR1 on four neuroblastoma cell lines via α-NETA, a recently described CMKLR1 inhibitor, dose-dependently reduced cell viability and clonogenicity." (PMID 30555465, 2018). "In our work, we observed that α-NETA, a small molecule inhibitor for CMKLR1, reduced the cell viability and clonogenicity of neuroblastoma cell lines." (PMID 29221117, 2017). "Comparable staining pattern for CMKLR1 was observed in other neuroblastoma cell lines using additional primary antibodies for confirmation." (PMID 29221117, 2017). "A total of 27 neuroblastoma tissue samples from all clinical stages and biological subsets were stained with antibodies detecting chemerin, CMKLR1 and GPR1." (PMID 29221117, 2017). "Our results demonstrate, for the first time, the presence of a fully active and functional chemerin/CMKLR1 axis in childhood neuroblastoma." (PMID 29221117, 2017). "Examining two neuroblastoma gene expression cohorts, we found a correlation between high expression of CMKLR1 and GPR1 and a decrease in overall survival probability." (PMID 29221117, 2017). "In neuroblastoma, a childhood tumor of the peripheral nervous system we identified correlations between high CMKLR1 and GPR1 expression and reduced overall survival probability." (PMID 29221117, 2017). "The effect of CMKLR1 inhibition on neuroblastoma cell lines was studied using the recently described CMKLR1 inhibitor α-NETA." (PMID 29221117, 2017). "Although we made several attempts to knock down/out CMKLR1 in neuroblastoma cell lines using both shRNA and the CRISPR/Cas9 system, we have established to date only one SK-N-AS cell line with a marked CMKLR1 downregulation." (PMID 29221117, 2017). "This study demonstrates the potential of the chemerin/CMKLR1 axis as a prognostic factor and possible therapeutic target in neuroblastoma." (PMID 29221117, 2017). "According to the same study, inhibition of the chemerin/CMKLR1 axis exhibited antitumor effects in vitro and in vivo, suggesting that the chemerin/CMKLR1 axis could be a potential therapeutic target for neuroblastoma." (PMID 30555465, 2018). "Furthermore, CMKLR1 expression was higher in neuroblastoma cohorts compared to benign neurofibroma and neural crest cells." (PMID 29221117, 2017). "Inhibition of the chemerin/CMKLR1 axis impaired neuroblastoma cell growth in vitro and in vivo." (PMID 29221117, 2017). "Pharmacological interventions targeting the chemerin/CMKLR1 signaling pathway may be an important adjuvant therapy for children with neuroblastoma, but further preclinical in vivo studies are warranted." (PMID 29221117, 2017). "We examined different neuroblastoma cell lines for the expression of CMKLR1, GPR1 and chemerin." (PMID 29221117, 2017).
neuroblastoma (continued). "Additionally, the results should be confirmed using CMKLR1 knockout neuroblastoma cell lines." (PMID 29221117, 2017). "Fluorescence labeling of CMKLR1 (green) and chemerin (red) displayed the membranous and cytoplasmic localization of CMKLR1 whereas chemerin was detected both in intra- and extracellular compartments indicating chemerin secretion in neuroblastoma primary tumor tissue." (PMID 29221117, 2017). "In vitro, expression of CMKLR1, chemerin mRNA/protein, and GPR1 was verified in neuroblastoma cell lines (as well as primary tumors) via real time-PCR and western blot analysis." (PMID 30555465, 2018). "Overall, CMKLR1 and GPR1 expression was shown to be a potentially viable indicator of prognosis in neuroblastoma patients." (PMID 30555465, 2018). "Immunofluorescence staining demonstrated the cellular distribution of CMKLR1 and GPR1 in the neuroblastoma cell line SH-SY5Y." (PMID 29221117, 2017). "Using RT-PCR and western blot we demonstrated expression of CMKLR1, GPR1 and chemerin mRNA and protein at varying levels in all neuroblastoma cell lines tested." (PMID 29221117, 2017). "The small molecule CMKLR1 antagonist α-NETA reduced the clonogenicity and viability of neuroblastoma cell lines indicating the chemerin/CMKLR1 axis as a promoting factor in neuroblastoma tumorigenesis." (PMID 29221117, 2017). "In the present study, we investigated the role of chemerin and its receptors CMKLR1 and GPR1 in neuroblastoma tumorigenesis." (PMID 29221117, 2017). "CMKLR1, GPR1, and chemerin RNA and protein were detected in neuroblastoma cell lines and neuroblastoma primary tumor tissue." (PMID 29221117, 2017). "Therefore, a potential role of chemerin/CMKLR1 in neuroblastoma angiogenesis could be hypothesized." (PMID 29221117, 2017). "The aim of the present study was to investigate the functional significance of chemerin, CMKLR1 and GPR1 in the neuroblastoma microenvironment and assess their potential as prognostic factors and therapeutic targets." (PMID 29221117, 2017). "IHC labeling of the macrophage marker CD68 as well as double IF-P staining of CD68 and CMKLR1 in neuroblastoma tissue demonstrated that while the majority of CMKLR1 is expressed by the tumors cells, CD68+ cells in the TME also express CMKLR1." (PMID 29221117, 2017). "Moreover, the expression of the chemerin receptors CMKLR1 and GRP1 was found to have an inverse correlation with the survival of neuroblastoma patients." (PMID 37895840, 2023). "Furthermore, expression of CMKLR1 and CCRL2 was found to be upregulated in neuroblastoma cohorts in comparison to benign counterparts, while increased CCRL2 expression was correlated to poor prognosis." (PMID 30555465, 2018). "While most of the known chemerin functions have been connected to CMKLR1-mediated signaling, we cannot exclude that chemerin mediated signaling in neuroblastoma cell lines is not at least partly mediated by GPR1." (PMID 29221117, 2017).
metabolic syndrome (7 papers, 2014 to 2023). A cluster of metabolic risk factors for CARDIOVASCULAR DISEASES and TYPE 2 DIABETES MELLITUS. "Chemerin/CMKLR1 plays important roles in inflammation, chemotaxis of immune cells, as well as in metabolic syndrome." (PMID 36624417, 2023). "CMKLR1 deficiency in mice is not related to changes in body weight, inflammation, glucose tolerance and dyslipidemia." (PMID 27548138, 2016). "Dyslipidemia may nevertheless affect hepatic CMKLR1 activity in females independent of NAFLD." (PMID 27548138, 2016).
pneumonia (7 papers, 2011 to 2025). An acute, acute and chronic, or chronic inflammation focally or diffusely affecting the lung parenchyma, caused by an infection in one or both of the lungs (by bacteria, viruses, fungi, or mycoplasma.). "When wild-type and CMKLR1 knock-out mice are infected by pneumonia virus of mice, the CMKLR1 deficient mice display higher mortality and morbidity, alteration of lung function, delayed viral clearance and increased neutrophilic infiltration." (PMID 23293638, 2012). "However, CMKLR1-deficient mice had an increased inflammatory response in lipopolysaccharide-induced acute lung inflammation and had delayed clearance of the virus and a higher mortality, in the pneumonia virus of mice model, as a result of the loss of the anti-inflammatory pathways involving CMKLR1." (PMID 29279348, 2018).
viral pneumonia (7 papers, 2011 to 2023). Inflammation of the lung parenchyma that is caused by a viral infection. "Previously, it was reported that Cmklr1-KO mice were more susceptible in a model of acute lipopolysaccharide-induced lung inflammation and viral pneumonia." (PMID 36883565, 2023). "Cmklr1 knock-out (Cmklr1-/-) mice have been reported to be protected against central nervous system inflammation, but they were more susceptible to lipopolysaccharide-induced lung inflammation and viral pneumonia." (PMID 24781986, 2014).
Hepatic steatosis (6 papers, 2014 to 2023). Steatosis is a term used to denote lipid accumulation within hepatocytes. "It was also reported that CMKLR1 null mice had less liver steatosis but this was most likely related to the reduced adiposity of these animals." (PMID 35449483, 2022). "Moreover, PI3K inhibition mitigated liver steatosis and KC-mediated inflammation due to the down-regulation of the chemerin receptor CMKLR1 in the liver." (PMID 36009862, 2022). "CMKLR1 deficient mice are not protected from liver steatosis in experimental NASH." (PMID 35449483, 2022). "Interestingly, hepatic CMKLR1 protein is reduced in the liver of human subjects suffering from hepatic steatosis and becomes upregulated by adiponectin, suggesting a protective role of the receptor under conditions of liver steatosis." (PMID 25121101, 2014). "In this study conducted on obese mice, we have explored: 1) CMKLR1 expression in the ileums; 2) CMKLR1 inhibitor α-NETA on body weight and intestinal mucosa integrity hence the impact on hepatic steatosis and pathway involved." (PMID 36624417, 2023). "In addition, Cmklr1-/- mice were found to have reduced hepatic steatosis on a low fat diet, but not on a high fat diet, whereas hepatic inflammation was reduced in Cmklr1-/- mice on both diets." (PMID 24781986, 2014).
Alzheimer disease (5 papers, 2018 to 2023). A progressive, neurodegenerative disease characterized by loss of function and death of nerve cells in several areas of the brain leading to loss of cognitive function such as memory and language. "In support, CMKLR1 deficiency improved memory in a mouse model of Alzheimer’s disease." (PMID 35711300, 2022).
colorectal cancer (5 papers, 2021 to 2025). A primary or metastatic malignant neoplasm that affects the colon or rectum. "CMKLR1 is involved in a number of additional metabolic processes, including angiogenesis of colorectal cancers." (PMID 39680574, 2024). "Colorectal cancer tissue displays increased levels of CMKLR1, correlating with tumor size." (PMID 34359687, 2021). "Increased concentration of CMKLR1 in colorectal cancer tissue was reported in our recent study." (PMID 34946244, 2021).
COVID-19 (5 papers, 2022 to 2024). A disease caused by infection with severe acute respiratory syndrome coronavirus 2. "GO and KEGG pathway analyses showed that inflammation-, immunity-, and infection-associated terms were enriched in db/db mice microglia, such as Il17ra, Il6ra, Cmklr1, Nlrp3, Trem2, Coronavirus disease-COVID-19, Epstein-Barr virus infection, phagosome and NF-κB signaling pathway." (PMID 35721719, 2022). "The clinical relevance of CMKLR1 as a marker of lung inflammation in ARDS was confirmed using RNA sequencing data, which showed that CMKLR1 expression is significantly increased in lung monocytes and macrophages in COVID-19 patients." (PMID 38543303, 2024).
diabetic nephropathy (5 papers, 2018 to 2021). "Additionally, CMKLR1 has also been implicated to play a pathophysiological role in diabetic nephropathy (DN)." (PMID 31379940, 2019). "In vivo, PPARγ agonist induced reductions of chemerin and/or CMKLR1 in diabetic rats which might be associated with the ameliorations of diabetic nephropathy." (PMID 30873215, 2019).
glioblastoma (5 papers, 2017 to 2024). The most malignant astrocytic tumor (WHO grade IV). "Chemerin expression and CMKLR1 levels have been found to be upregulated in cases of cancer cells (glioblastoma, mesothelioma, and squamous cell carcinoma of the oral tongue), exacerbating tumor expansion and metastasis." (PMID 39104601, 2024). "The chemerin/CMKLR1 axis promotes the interaction between glioblastoma (GBM) cells and TAMs by activating NF-κB signaling." (PMID 38280909, 2024).